ENHO (energy homeostasis associated)
Description:
Involved in the regulation of glucose homeostasis and lipid metabolism.
Synonyms: C9orf165; UNQ470
Tractability: Antibody: UniProt places it where antibodies can reach, with high confidence; UniProt predicts a signal peptide or a membrane-spanning region; its Gene Ontology location is reachable by antibodies, with medium confidence.
Gene: Protein-coding gene on chromosome 9 (34,521,043 to 34,523,174, reverse strand). Ensembl gene ENSG00000168913.
Subcellular location: Secreted
Gene Ontology:
Molecular function: hormone activity
Biological process: energy homeostasis; positive regulation of Notch signaling pathway; signal transduction
Cellular component: extracellular region; plasma membrane
Genetic constraint (gnomAD): Loss-of-function variants: 5 observed, 4.36 expected, observed/expected ratio (o/e) 1.15, 90% interval 0.58 to 1.87. That is too few expected variants to judge how well the gene tolerates losing a copy. Missense variants: 86 observed, 102.42 expected, observed/expected ratio (o/e) 0.84, 90% interval 0.7 to 1. Synonymous variants: 45 observed, 45.35 expected, observed/expected ratio (o/e) 0.99, 90% interval 0.78 to 1.27.
Homologues: Orthologues: chimpanzee ENHO (100% identical), guinea pig ENHO (100% identical), mouse Enho (100% identical), rabbit ENHO (100% identical), rat Enho (100% identical), dog ENHO (99% identical), pig ENHO (96% identical).
Diseases named in the same sentence as ENHO in open-access papers:
ENHO is named in the same sentence as 22 diseases in open-access papers, as found by Europe PMC text mining. Sharing a sentence is not in itself a finding about the gene and the disease. The quoted sentences say what the papers report.
dementia (2 papers, 2021 to 2023). Loss of intellectual abilities interfering with an individual's social and occupational functions. "While ENHO expression appears to decline with aging, expression does not appear to be markedly different between people with or without dementia." (PMID 37945652, 2023). "ENHO expression is not affected by dementia status in humans." (PMID 34462439, 2021).
Alzheimer disease (1 paper, 2021). A progressive, neurodegenerative disease characterized by loss of function and death of nerve cells in several areas of the brain leading to loss of cognitive function such as memory and language. "ENHO expression in the human brain also correlated with common neurodegenerative disorders (Parkinson’s disease, Huntington’s disease, and Alzheimer’s disease)." (PMID 34462439, 2021).
Behçet’s disease (1 paper, 2019). "ENHO transcript levels negatively correlated with serum TG in the studied HD group and subjects with Behçet’s disease as well as plasma adropin negatively associated with TG and atherogenic index in our previous study on HD patients." (PMID 31775661, 2019).
diabetic nephropathy (1 paper, 2018). "Parameters chosen as explanatory variables for dyslipidaemia by K/DOQI included gender, age, RRT duration, diabetic nephropathy, BMI, and the TT genotype of ENHO rs2281997." (PMID 30413149, 2018). "The parameters chosen as explanatory variables for atherogenic dyslipidaemia included gender, age, RRT duration, diabetic nephropathy, BMI, and the CC genotype of ENHO rs2281997." (PMID 30413149, 2018).
dyslipidaemia (1 paper, 2018). "All HD patients of the discussed subgroup presented atherogenic dyslipidaemia, similar to those bearing the T allele of ENHO rs2281997." (PMID 30413149, 2018). "The variant allele (T) of ENHO rs2281997 was associated with the hyper-LDL cholesterolaemic pattern of dyslipidaemia by K/DOQI." (PMID 30413149, 2018). "We have demonstrated, for the first time, that the TT genotype of ENHO rs2281997 was associated with dyslipidaemia by K/DOQI criteria at the third BADGE class for genetic association." (PMID 30413149, 2018). "However, in the subgroup of HD patients showing atherogenic dyslipidaemia, the T allele of ENHO rs2281997 was associated with a 1.6-fold lower cardiovascular mortality." (PMID 30413149, 2018). "ENHO, RXRA, and LXRA SNPs, separately or jointly, are associated with dyslipidaemia, myocardial infarction, and survival in HD patients." (PMID 30413149, 2018). "A gene-gene interaction was noted among the ENHO rs2281997, RXRA rs10776909, and LXRA rs7120118 polymorphisms in relation to dyslipidaemia by K/DOQI." (PMID 30413149, 2018). "Patients with atherogenic dyslipidaemia showed a lower frequency of the T allele of ENHO rs2281997 than patients without this type of dyslipidaemia at the fourth BADGE class for genetic association." (PMID 30413149, 2018). "ENHO rs72735260 variants showed no direct association with the type of dyslipidaemia, analysed comorbidities, and mortality of HD patients." (PMID 30413149, 2018). "In this study, LXRA, ENHO, and RXRA SNPs interacted in the occurrence of both types of dyslipidaemia." (PMID 30413149, 2018). "Therefore, we conclude that our findings indicate that ENHO, RXRA, and LXRA are involved in the genetic architecture of dyslipidaemia in HD patients." (PMID 30413149, 2018). "ENHO, RXRA, and LXRA showed epistatic interactions in dyslipidaemia." (PMID 30413149, 2018).
dyslipidemia (1 paper, 2021). "Furthermore, a study conducted on HD patients with dyslipidemia showed that a certain variant of ENHO gene is associated with the hyper LDL cholesterolemic pattern of dyslipidemia, but contrary to expectations it was also associated with lower cardiovascular mortality." (PMID 33920330, 2021).
familial Mediterranean fever (1 paper, 2025). Familial Mediterranean fever (FMF) is an autoinflammatory disorder characterized by recurrent short episodes of fever and serositis resulting in pain in the abdomen, chest, joints and muscles. "This study sheds light on the role of ENHO expression and Adropin in the pathophysiology of Familial Mediterranean Fever (FMF)." (PMID 40076990, 2025).
glioma (1 paper, 2022). A benign or malignant brain and spinal cord tumor that arises from glial cells (astrocytes, oligodendrocytes, ependymal cells). "No published evidence was available as to the roles of the remaining eight underexpressed gene signatures (CHST9, CSDC2, ENHO, FERMT1, IGFN1, LINC00836, MGAT4C and SHANK2) regarding glioma pathogenesis or prognosis." (PMID 35456975, 2022).
metastatic tumor (1 paper, 2025). "Together, these findings support the notion that ENHO expression has a protective role, potentially contributing to a less invasive and metastatic tumor PAAD phenotype." (PMID 40647442, 2025).
pancreatic adenocarcinoma (1 paper, 2025). "This, alongside the previous discussion about ENHO’s immunomodulatory role, is a plausible explanation for why increased ENHO expression is associated with better overall survival in pancreatic adenocarcinoma patients." (PMID 40647442, 2025).
pancreatic cancer (1 paper, 2025). "This marked reduction suggests that ENHO dysregulation is a likely contributor to the development and progression of pancreatic cancer." (PMID 40647442, 2025).
periodontitis (1 paper, 2024). An acute or chronic inflammatory process that affects the tissues that surround and support the teeth. "MR analysis corroborated the inferences drawn from scRNA-seq, identifying ten causal gene markers associated with periodontitis, including LIMA1, PEA15, TMEM158, CMTM6, PDP1, FFAR4, VAC14, and ENHO." (PMID 39830509, 2024).
tumor (3 papers, 2023 to 2025). "The data also implies that ENHO is involved in a dual state of immunomodulation, where immune activation is promoted yet counteracted by tumor escape mechanisms." (PMID 40647442, 2025). "At the same time, transfection of the ENHO gene into MC38 colon cancer cells has shown inhibition of tumor growth in vivo." (PMID 40647442, 2025). "A recent study demonstrated that transfection of the ENHO gene into colon cancer (MC38) cells suppressed tumor growth in vivo while promoting an increase in M1 macrophages." (PMID 39906123, 2025). "In the present study, we observed that ENHO expression was significantly lower in tumor tissues compared with normal pancreatic tissues (p = 3.88 × 10−68)." (PMID 40647442, 2025). "Based on the analysis by TCGA, ENHO mRNA level substantially decreased in tumor tissues compared with normal colon tissues." (PMID 37904094, 2023). "The transcriptional level of ENHO was lower in tumor tissues than in the surrounding normal tissues." (PMID 37904094, 2023). "Pathway enrichment analysis further supported ENHO’s potential tumor-suppressive role in PAAD." (PMID 40647442, 2025). "High ENHO expression was negatively correlated with pro-oncogenic pathways such as PI3K/AKT, suggesting that ENHO may hinder tumor growth by suppressing these pathways." (PMID 40647442, 2025). "A positive co-expression of ENHO with TNFRSF17, a B-cell maturation factor, suggests that ENHO may facilitate the recruitment of more mature B cells into the tumor microenvironment, thereby contributing to anti-tumor effects." (PMID 40647442, 2025). "Additionally, ENHO was positively co-expressed with MHC class II presentation genes (including HLA-DMA, HLA-DOA, HLA-DPA1, HLA-DPB1, and HLA-DRB1), supporting its role in promoting anti-tumor immunity." (PMID 40647442, 2025). "Moreover, ENHO’s negative correlations with other immune checkpoint molecules, such as CD276 (B7-H3) and NT5E (CD73), which are implicated in immune escape by suppressing T-cell activity and promoting regulatory T-cell (Treg) responses, further reinforce its potential anti-tumor role." (PMID 40647442, 2025).
cancer (2 papers, 2023 to 2025). A tumor composed of atypical neoplastic, often pleomorphic cells that invade other tissues. "Conversely, low ENHO expression was associated with the activation of pathways related to epithelial-mesenchymal transition (EMT), extracellular matrix organization, and cancer metastasis." (PMID 40647442, 2025). "Finally, while comparisons with other cancers provide useful context, discrepancies in the literature highlight the need for further research to clarify ENHO’s role across different malignancies." (PMID 40647442, 2025). "Therefore, the effect of ENHO overexpression in carcinoma cells on the shaping of local adaptive immune function needs to be evaluated comprehensively." (PMID 37904094, 2023).
vasculopathy (1 paper, 2024). "In our investigation, we observed a decrease in ENHO expression in SSc skin tissues, suggesting a potential involvement of ENHO in the pathogenesis of endothelial cell dysfunction and vasculopathy in SSc." (PMID 38348042, 2024).
ENHO also shares sentences with these, for which no sentence is quoted: coronary artery disease (1 paper); Huntington disease (1); metabolic disease (1); myocardial infarction (1); Obesity (1); Parkinson disease (1); type 2 diabetes mellitus (1).